ZDHHC1 (zDHHC palmitoyltransferase 1)
Description:
Palmitoyltransferase that catalyzes the addition of palmitate onto various protein substrates, such as NCDN and NLRP3. Has a palmitoyltransferase activity toward NCDN and regulates NCDN association with endosome membranes through this palmitoylation (By similarity). Acts as an activator of the NLRP3 inflammasome by mediating palmitoylation of 'Cys-130' and 'Cys-958' of NLRP3, thereby promoting NLRP3 phosphorylation and activation by NEK7. Also has a palmitoyltransferase activity-independent function in DNA virus-triggered and CGAS-mediated innate immune response. Functions as an activator of STING1 by promoting its cGAMP-induced oligomerization and the recruitment of downstream signaling components.
Synonyms: DHHC-1; C16orf1; ZNF377; HSU90653
Tractability: Antibody: UniProt places it where antibodies can reach, with medium confidence; UniProt predicts a signal peptide or a membrane-spanning region. PROTAC: ubiquitination databases record sites on it.
Gene: Protein-coding gene on chromosome 16 (67,394,152 to 67,416,833, reverse strand). Ensembl gene ENSG00000159714.
Subcellular location: Endosome membrane; Endoplasmic reticulum membrane; Golgi apparatus
Subcellular location (Human Protein Atlas): Cytosol
Gene Ontology:
Molecular function: palmitoyltransferase activity; protein binding; protein-cysteine S-palmitoyltransferase activity; DNA binding
Biological process: antiviral innate immune response; positive regulation of defense response to virus by host; positive regulation of NLRP3 inflammasome complex assembly; protein targeting to membrane
Cellular component: endoplasmic reticulum; endoplasmic reticulum membrane; extracellular exosome; Golgi apparatus; endosome membrane
Genetic constraint (gnomAD): Loss-of-function variants: 45 observed, 44.74 expected, observed/expected ratio (o/e) 1.01, 90% interval 0.79 to 1.29. The upper end of that interval is the gene's LOEUF score, 1.29, which puts it in group 5 of 6, group 1 being the genes least tolerant of losing a copy. Missense variants: 647 observed, 602.03 expected, observed/expected ratio (o/e) 1.07, 90% interval 1.01 to 1.15. Synonymous variants: 291 observed, 254.86 expected, observed/expected ratio (o/e) 1.14, 90% interval 1.04 to 1.26.
Homologues: Orthologues: macaque ZDHHC1 (96% identical), dog ZDHHC1 (91% identical), pig ZDHHC1 (89% identical), mouse Zdhhc1 (87% identical), guinea pig ZDHHC1 (87% identical), rabbit ZDHHC1 (79% identical), chimpanzee ZDHHC1 (76% identical), rat Zdhhc1 (69% identical), zebrafish zdhhc1 (49% identical), tropical clawed frog zdhhc1 (20% identical), Drosophila melanogaster CG1407 (13% identical), Caenorhabditis elegans dhhc-2 (13% identical), and 7 more. Paralogues in human: ZDHHC11 (29% identical), ZDHHC11B (29% identical), ZDHHC14 (17% identical), ZDHHC3 (17% identical), ZDHHC19 (15% identical), ZDHHC7 (15% identical), ZDHHC18 (15% identical), ZDHHC9 (15% identical), ZDHHC12 (14% identical), ZDHHC6 (14% identical), ZDHHC2 (13% identical), ZDHHC20 (13% identical), and 5 more.